FBXO31 (F-box protein 31)
Diseases named in the same sentence as FBXO31 in open-access papers (continued):
Sharing a sentence is not in itself a finding about the gene and the disease.
tumor (continued). "ZNF217 is proved to be a central role in cancer development, and FBXO31 is proved to be a candidate tumor suppressor gene, by generating Skp Cullin F-box containing SCF complex, it causes cell senescence and has consistent tumor suppressor attributes." (PMID 32318558, 2020). "FBXO31 was initially regarded as a candidate tumor suppressor." (PMID 25115392, 2014). "Ectopic expression of FBXO31 dramatically inhibited xenograft tumor growth in nude mice." (PMID 25115392, 2014). "Further analysis showed that the decreased expression of FBXO31 was significantly associated with a higher clinical stage of GC, suggesting that FBXO31 might play an important role in tumor development and progression." (PMID 25115392, 2014). "The role of FBXO31 in tumorigenesis and development seems to be different in different tumor type." (PMID 25115392, 2014). "The E3 ligase FBXO31-SCF has been introduced as a tumor suppressor and cell cycle regulator." (PMID 23469015, 2013). "The data showed that the expression level of FBXO31 was significantly associated with tumor size (P=0.022), depth of tumor infiltration (T stage, P=0.024) and tumor grade (P=0.012), but not with age, gender, and tumor local lymph node metastasis (N stage)." (PMID 25115392, 2014). "Therefore, FBXO31 played a very important role in inhibiting tumor formation." (PMID 25115392, 2014). "Following FBXO31 transfection into CD147 (+) cells, sphere formation tests were used to identify the tumor stemness features." (PMID 40822976, 2025). "MiR-29c was down-regulated in tumor tissues and serum samples of ESCC patients and has also been found to reverse 5-FU resistance by silencing F-box only protein 31 (FBXO31)." (PMID 34881242, 2021). "Therefore, FBXO31 may also exert its role in tumorigenesis depending on tumor cell types." (PMID 30341246, 2019). "As for FBXO5, FBXO22, FBXO28, FBXO31 and FBXO45, they may be the independent poor prognostic factors of BC and the expression levels of which were closely related to different tumor stages." (PMID 33622332, 2021). "In addition, our bioinformatics analysis revealed that miR-20a regulated several cancer-related genes, particularly tumor suppressor genes, such as PTEN, BCL2L11, FBXO31, and DUSP2." (PMID 33125430, 2020). "26/52 samples showed the inverse trend of decreased FBXO31 and increased miR-20a expression in tumor tissues compared with non-cancerous tissue." (PMID 25115392, 2014). "In particular, FBXO31 was recently identified not by deletion mapping, but by identification of its ability to induce senescence in tumor cells." (PMID 18416817, 2008). "To determine whether FBXO31 promotes tumor growth in vivo, we subcutaneously injected Panc-1 cells with or without FBXO31 overexpression into the flank of nude mice." (PMID 38216561, 2024).
cancer (13 papers, 2014 to 2025). A tumor composed of atypical neoplastic, often pleomorphic cells that invade other tissues. "Studies suggest that FBXO31 affects the growth of cancer by playing a crucial part in biological processes such as DNA repair, cell cycle, cell growth, and metastasis." (PMID 40822976, 2025). "It has been suggested that FBXO31 plays a key role in biological process of DNA repair, cell cycle, cell growth and metastasis, thus contributing to cancer development." (PMID 38216561, 2024). "FBXO31 belongs to the F-box family, which is essential for cancer development." (PMID 40822976, 2025). "Furthermore, a small number of studies implied that FBXO31 functioned as an oncoprotein to promote oncogenesis and cancer progression in lung and esophageal cancer." (PMID 38216561, 2024). "Among the cancer-specific targets of the isomiR, we highlight FBXO31 and MFN2." (PMID 36688696, 2023). "Similar to our findings using microarray analysis, FoxO was necessary for the cancer-induced upregulation of Cebpb, Fos, Fbxo31 and Psma2, and was necessary for the cancer-induced downregulation of Col6a2, Myoz3 and Tnc (interaction effect, p < 0.05, AAV9-ev C26 vs. AAV9-d.n.FoxO C26, p < 0.05)." (PMID 25539728, 2014). "m6A modification by METTL3 stabilizes FBXO31 mRNA by binding to YTHDF1, which increases FBXO31 expression and promotes proteasome‐dependent degradation of sirtuin 2 (SIRT2), leading to cancer progression." (PMID 40448344, 2025). "FBXO31, a member of F-box family to comprise of SCF complex, contributes to a pivotal role in cancer progression." (PMID 38216561, 2024). "FAS, C16orfS4, FBXO31, ACSS3, ZCCHC8 and THBS3 were found to help the metastatic cancer cells survive from the immune surveillance." (PMID 35685372, 2022).
cardiovascular diseases (1 paper, 2022). "Thus, FBXO31 may be a novel therapeutic target for endothelial senescence-related cardiovascular diseases." (PMID 35453604, 2022).
immune dysfunction (1 paper, 2025). "Specifically, we propose that FBXO31 helps clear oxidatively damaged proteins, thereby preserving cellular function and mitigating immune dysfunction." (PMID 41194984, 2025).
neurological disorders (1 paper, 2023). "These included genes that encode a component of the SCF ubiquitination complex (FBXO31), an enzyme involved in fatty acid oxidation (HADH) and a member of the KCTD family (KCTD7), mutations in which have been linked to several neurological disorders." (PMID 37818590, 2023).
FBXO31 also shares sentences with these, for which no sentence is quoted: autism (1 paper); colon cancer (1); colorectal cancer (1); congenital hydrocephalus (1); esophageal squamous cell carcinoma (1); neurodevelopmental disorder (1); Ovarian Insufficiency (1).